APOA5 (apolipoprotein A5)
Description:
Minor apolipoprotein mainly associated with HDL and to a lesser extent with VLDL. May also be associated with chylomicrons. Important determinant of plasma triglyceride (TG) levels by both being a potent stimulator of apo-CII lipoprotein lipase (LPL) TG hydrolysis and an inhibitor of the hepatic VLDL-TG production rate (without affecting the VLDL-apoB production rate) (By similarity). Activates poorly lecithin:cholesterol acyltransferase (LCAT) and does not enhance efflux of cholesterol from macrophages. Binds heparin.
Synonyms: ApoA-V; RAP3; APOAV
Tractability: Antibody: UniProt places it where antibodies can reach, with high confidence; its Gene Ontology location is reachable by antibodies, with high confidence; UniProt predicts a signal peptide or a membrane-spanning region. PROTAC: its protein half-life has been measured.
Gene: Protein-coding gene on chromosome 11 (116,789,014 to 116,793,026, reverse strand). Ensembl gene ENSG00000110243.
Subcellular location: Secreted; Early endosome; Late endosome; Golgi apparatus, trans-Golgi network
Pathways (Reactome):
Metabolism of proteins: Post-translational protein phosphorylation; Regulation of Insulin-like Growth Factor (IGF) transport and uptake by Insulin-like Growth Factor Binding Proteins (IGFBPs)
Transport of small molecules: Assembly of active LPL and LIPC lipase complexes; Chylomicron remodeling
Metabolism: PPARA activates gene expression
Gene Ontology:
Molecular function: enzyme binding; heparin binding; lipase activator activity; lipase binding; lipid binding; lipoprotein lipase activator activity; lipoprotein particle receptor binding; low-density lipoprotein particle receptor binding; phosphatidylcholine binding; phospholipid binding; protein binding; cholesterol transfer activity; phosphatidylcholine-sterol O-acyltransferase activator activity
Biological process: acylglycerol homeostasis; cholesterol homeostasis; lipid transport; positive regulation of fatty acid biosynthetic process; positive regulation of lipid catabolic process; positive regulation of triglyceride catabolic process; positive regulation of very-low-density lipoprotein particle remodeling; tissue regeneration; triglyceride catabolic process; triglyceride homeostasis; triglyceride metabolic process; very-low-density lipoprotein particle clearance; cholesterol efflux; cholesterol metabolic process; phospholipid efflux; positive regulation of receptor-mediated endocytosis; lipoprotein metabolic process
Cellular component: chylomicron; early endosome; extracellular region; high-density lipoprotein particle; late endosome; low-density lipoprotein particle; very-low-density lipoprotein particle; endoplasmic reticulum lumen; extracellular vesicle; Golgi apparatus
Genetic constraint (gnomAD): Loss-of-function variants: 26 observed, 31.49 expected, observed/expected ratio (o/e) 0.83, 90% interval 0.6 to 1.15. The upper end of that interval is the gene's LOEUF score, 1.15, which puts it in group 5 of 6, group 1 being the genes least tolerant of losing a copy. Missense variants: 450 observed, 487.98 expected, observed/expected ratio (o/e) 0.92, 90% interval 0.85 to 1. Synonymous variants: 186 observed, 199.63 expected, observed/expected ratio (o/e) 0.93, 90% interval 0.83 to 1.05.
Homologues: Orthologues: chimpanzee APOA5 (99% identical), macaque APOA5 (96% identical), rabbit APOA5 (80% identical), pig APOA5 (79% identical), dog APOA5 (78% identical), guinea pig APOA5 (75% identical), mouse Apoa5 (73% identical), rat Apoa5 (71% identical), tropical clawed frog apoa5 (35% identical). Paralogues in human: APOA4 (24% identical), APOA1 (17% identical), APOE (13% identical).
Diseases named in the same sentence as APOA5 in open-access papers:
APOA5 is named in the same sentence as 104 diseases in open-access papers, as found by Europe PMC text mining. Sharing a sentence is not in itself a finding about the gene and the disease. The quoted sentences say what the papers report.
hypertriglyceridemia (104 papers, 2006 to 2026). A laboratory test result indicating elevated triglyceride concentration in the blood. "It is an effective regulator of plasma triglyceride (TG) and HDL cholesterol (HDL-C) levels, and genetic variants in APOA5 are strong predictors of hypertriglyceridemia-related cardiovascular risk." (PMID 41179497, 2025). "Homozygous mutations in the APOA5 gene constitute a rare cause of monogenic hypertriglyceridemia, or familial chylomicronemia syndrome (FCS)." (PMID 38872171, 2024). "Clinical case reports described severe hypertriglyceridemia in two patients harboring an APOA5 frameshift mutation that truncates APOA5 by 35 residues." (PMID 38880127, 2024). "Accumulating evidence has also determined that rs662799 genetic variants located upstream of the APOA5 promoter are linked to hypertriglyceridemia and increase the risk of MetS with its individual components." (PMID 38581036, 2024). "Collectively, these results suggested that restoration of ApoA5 in knockout hamsters not only ameliorated ApoA5 deficiency-induced hypertriglyceridemia and hepatic steatosis, but also rescued the abnormalities in other metabolic tissues." (PMID 38505614, 2024). "We report a case of a 25-years old Afghani male presenting with acute pancreatitis due to severe hypertriglyceridemia up to 29.8 mmol/L caused by homozygosity in APOA5 (c.427delC, p.Arg143Alafs*57)." (PMID 38872171, 2024). "Among the single nucleotide polymorphisms (SNPs) in APOA5, the − 1131T > C variant (rs662799) in the promoter region was specifically associated with hyperglyceridemia and resulted in an increased risk of MetS, depending on the different populations." (PMID 38581036, 2024). "APOA5 is vital for TG breakdown, and its absence leads to hypertriglyceridemia and elevates the risk of cardiovascular diseases." (PMID 38521668, 2024). "Humans with biallelic APOA5 loss-of-function mutations have severe hypertriglyceridemia, and APOA5 mutations increase the risk of coronary heart disease." (PMID 37824203, 2023). "Apolipoprotein A5 (APOA5) gene variations and hypertriglyceridemia have been linked in numerous studies; however, the relation between APOA5 variants and HDL cholesterol levels has received less attention." (PMID 36975891, 2023). "We suspect that the ANGPTL3/8 mAb, by increasing intracapillary LPL levels, will be highly effective in treating hypertriglyceridemia in patients with APOA5 deficiency." (PMID 37824203, 2023). "Of note, a common APOA5 missense mutation in Chinese populations (with an allelic frequency of 7%) causes both severe hypertriglyceridemia and increases the risk of coronary heart disease." (PMID 37824203, 2023). "The APOA5 gene mutation results in hypertriglyceridemia or hyperlipoproteinemia type 5, which was in line with the diagnosis of hypertriglyceridemia based on the patient's blood test." (PMID 37288251, 2023). "APOA5 is clinically important; APOA5 mutations result in hypertriglyceridemia and an increased risk of coronary heart disease." (PMID 37824203, 2023). "Why apolipoprotein AV (APOA5) deficiency causes hypertriglyceridemia has remained unclear, but we have suspected that the underlying cause is reduced amounts of lipoprotein lipase (LPL) in capillaries." (PMID 37824203, 2023). "Variants in the APOA5 gene affected TG concentrations and the entire lipoprotein subclass distribution and caused hypertriglyceridemia." (PMID 35928108, 2022). "The APOA5 c.553G > T, p.Gly185Cys, also known as rs2075291, has been found to be associated with hypertriglyceridemia in Asians." (PMID 36312279, 2022). "Studies in human and mice have revealed that apoA5 deficiency are associated with severe hypertriglyceridemia." (PMID 36034782, 2022). "Among the genotyped participants, 6.88% of the total had a CC or CG genotype of rs3135506 (APOA5) with the dominant C genotype being the risk allele for its association with hypertriglyceridemia and cardiovascular diseases." (PMID 36050800, 2022).
hypertriglyceridemia (continued). "ApoA5 was previously linked to reduced levels of plasma TG, and mutations in the APOA5 gene are linked to hypertriglyceridemia." (PMID 34710432, 2022). "The APOA5 SNP rs2075291 (c.553G>T; p.185Gly>Cys) can be considered a susceptibility factor for hypertriglyceridemia and CAD." (PMID 35743896, 2022). "APOA5 is known to affect triglyceride metabolism, and the G allele of rs662799 increases the risk of hypertriglyceridemia (OR 6.37, 95% CI 4.08–9.95) in the Taiwanese population." (PMID 35468744, 2022). "Apo-A5 is known to decrease plasma TG levels as certain variants of the APOA5 gene have been associated with hypertriglyceridemia." (PMID 34436472, 2021). "Because liver X receptor (LXR) agonists decrease ApoA5 expression and cause hypertriglyceridemia, we investigated the effect of the prototypical LXR agonist T0901317 on human primary hepatocytes." (PMID 33762177, 2021). "In 2010, we showed a 2-fold enrichment of rare heterozygous variants in four candidate genes, including LPL and APOA5 in patients with hypertriglyceridemia." (PMID 32793115, 2020). "We identified homozygous mutation of c.553G > T in APOA5 gene, which was reported to be pathogenic and homozygotes manifest severe hypertriglyceridemia (mean TG = 2292 ± 447 mg/dL)." (PMID 33246467, 2020). "Deficiency of ApoA5 results in hypertriglyceridemia, whereas overexpression of ApoA5 leads to a reduction in triglyceride levels." (PMID 32322166, 2020). "Point mutations in APOA5 yield incomplete assembly of apoA-V protein, and were observed mostly in patients with hypertriglyceridemia." (PMID 30606120, 2019). "In the current study, we demonstrated that mice carrying human APOA5 c.553G>T variant had postprandial hypertriglyceridemia." (PMID 29425239, 2018). "In our previous report, we characterized the association between APOA5 c.553G>T variant and hypertriglyceridemia." (PMID 29425239, 2018). "Our previous report described an APOA5 variant, c.553G>T (rs2075291, Gly185 > Cys) that is associated with hypertriglyceridemia." (PMID 29425239, 2018). "The -1131T>C and c.553G>T polymorphisms were associated with hypertriglyceridemia in the study population, but only the -1131T>C polymorphism directly affected apoA5 concentrations." (PMID 29211729, 2017). "The -1131T>C and c.553G>T polymorphisms were associated with hypertriglyceridemia in this study population, but only the -1131T>C polymorphism directly affected apoA5 concentrations." (PMID 29211729, 2017). "The presence of the CC genotype of the APOA5 -1131T>C polymorphism was associated with a higher risk of hypertriglyceridemia [OR 3.322 (95% CI 2.421–4.559); p<0.001] after adjusting for age, sex, BMI, smoking, and drinking." (PMID 29211729, 2017). "In humans, a mutation in APOA5, which generates a truncated apoAV, has been associated with severe hypertriglyceridemia and hyperchylomicronemia." (PMID 27716220, 2016). "As revealed in our study, genetic variants appear to play an important role in the development of severe gestational hypertriglyceridemia, and, p.G185C mutation in APOA5 gene appears to be the most common variant implicated in the Chinese population." (PMID 26079787, 2015). "In mice, over expression of Apoa5 leads to decreased concentrations of TG in plasma, whereas a shortage of apoA5 causes hypertriglyceridemia, a risk factor for atherosclerosis and CHD." (PMID 26309253, 2015). "This functional variant occurs in the coding region of APOA5 gene and causes a substitution of a cysteine by a glycine residue, was suggested as prognostic indicators for hypertriglyceridemia risk in Chinese." (PMID 25909077, 2015). "The apolipoprotein A5 gene (APOA5) -1131 T > C polymorphism is associated with mild hypertriglyceridemia in type 2 diabetic subjects, and interacts with dietary fat in the determination of triglyceride concentrations." (PMID 24690159, 2014). "Naturally occurring polymorphisms of APOA5 are associated with hypertriglyceridemia, which is a component of MS." (PMID 23509746, 2013).
hypertriglyceridemia (continued). "The Q97X mutation of the APOA5 gene in homozygous status is responsible for the severe hypertriglyceridemia in this family." (PMID 23151256, 2012). "A recent targeted resequencing study conducted on patients with severe hypertriglyceridemia (HTG) for APOA5 detected an abundance of rare variants in HTG patients with T2D in comparison to those without T2D (25% vs. 6.1%, p = 0.037)." (PMID 22623978, 2012). "The APOA5 S19W variant has been previously associated with hypertriglyceridemia as well as with plasma HDL-C levels." (PMID 19878569, 2009). "Lastly, the prevalence of hypertriglyceridemia was higher in carriers of the APOA5 Trp19 allele (35%) than in carriers of the APOC3 -482T (23%) or APOC3 3238G (22%) alleles and thus increased the probability of fulfilling the definition of metabolic syndrome." (PMID 18789138, 2008). "We apply the proposed method to the hypertriglyceridemia study and identifies 3 haplotypes in the apolipoprotein A5 gene that are associated with increased risk for hypertriglyceridemia." (PMID 16907993, 2006). "Mutations in genes encoding lipoprotein lipase, apolipoprotein C-II (APOC2), apolipoprotein A-V (APOA5), and other enzymes involved in lipid metabolism have been associated with severe hypertriglyceridemia, particularly when triggered by medications or metabolic stress." (PMID 40862038, 2025). "These strategies could address the underappreciated connection between hypertriglyceridemia and neurological outcomes, particularly in patients with specific APOA5 genetic variants associated with elevated stroke susceptibility." (PMID 40869228, 2025). "We have also explored the therapeutic potential of antibodies or inhibitors targeting the A3/8 complex as a promising avenue for managing hypertriglyceridemia-related genetic conditions such as APOA5 or CREBH deficiencies, as well as for hyperlipidemia in a broader patient population." (PMID 38521668, 2024). "Although the mechanisms causing hypertriglyceridemia are not fully understood, certain genetic mutations, such as Apolipoprotein E mutations, APOA5 mutation, and APOC2 mutation, may be involved, leading to protein defects and function loss." (PMID 39267857, 2024). "Apolipoprotein AV (APOA5) deficiency causes hypertriglyceridemia in mice and humans." (PMID 38880127, 2024). "Apoa5 has been identified as a direct downstream target of PPARα and encodes for an apolipoprotein that aids in regulating triglyceride homeostasis, with the downregulation of this protein resulting in hypertriglyceridemia in mammals." (PMID 39453152, 2024). "Given the severity of the hypertriglyceridemia in Apoa5–/– mice, we began with a simple hypothesis: that APOA5 deficiency reduces the amounts of LPL within capillaries." (PMID 37824203, 2023). "Additionally, patients with hypertriglyceridemia who carried the APOA5 -1131T>C mutation showed smaller LDL particle sizes, as well as higher ox-LDL and higher ba-PWV values." (PMID 36975891, 2023). "Moderate hypertriglyceridemia and a loss-of-function mutation in apoA5 are commonly observed." (PMID 35144640, 2022). "APOA5 deficiency leads to hypertriglyceridemia, which may reflect its role in the efficient association of TRL with LPL or GPIHBP1 on endothelial cells, possibly because APOA5 interferes with an inhibitory effect of ANGPTL3/ANGPTL8 on this association." (PMID 34981790, 2022). "APOA5 genetic variants are associated with hypertriglyceridemia." (PMID 35664336, 2022). "Given that knockout of Apoa5 in mice increases plasma TG level, and mutation at APOA5 gene causes hypertriglyceridemia and elevated TC19,22, GATA4 may affect TG and TC homeostasis through APOA5." (PMID 35046404, 2022). "Recent studies have revealed that APOA5 could affect cholesterol homeostasis and could cause hypertriglyceridemia." (PMID 30606120, 2019).
hypertriglyceridemia (continued). "Recent studies have revealed that APOA5 could affect cholesterol homeostasis and could cause hypertriglyceridemia it is possible that statin therapy in these patients have more effect on TG metabolism given its effect on cholesterol hemostasis." (PMID 30606120, 2019). "This human APOA5 c.553G>T transgenic knock-in mice could be used as platform to study the perturbations in postprandial hypertriglyceridemia due to APOA5 c.553G>T variant." (PMID 29425239, 2018). "In addition, we analyzed the frequencies of 10 variant alleles in APOA1, APOA2, APOA4, and APOA5 that have been consistently linked to hypertriglyceridemia and elevated risks of CAD." (PMID 30076208, 2018). "Our study demonstrates that magnolol could efficiently reduce the postprandial plasma triglyceride level in APOA5 c.553G>T variant carrier mice and facilitate triglyceride metabolism in mild postprandial hypertriglyceridemia." (PMID 29425239, 2018). "In summary, magnolol could effectively lower the plasma triglyceride levels in APOA5 c.553G>T variant carrier mice and facilitate the triglyceride metabolism in postprandial hypertriglyceridemia." (PMID 29425239, 2018). "Our data indicate that magnolol could increase LPL activity in cells and reduce the plasma triglyceride level in APOA5 c.553G>T variant carrier mice and facilitate triglyceride metabolism in mild hypertriglyceridemia." (PMID 29425239, 2018). "Therefore, we aimed to evaluate the association of APOA5 SNPs, including -1131T>C and c.553G>T, with hypertriglyceridemia and apoA5 concentrations in a Korean population." (PMID 29211729, 2017). "Inherited deficiency of the APOA5 gene in humans leads to severe hypertriglyceridemia." (PMID 28934253, 2017). "Similarly, the presence of the T allele of the APOA5 c.553G>T polymorphism was associated with a higher risk of hypertriglyceridemia [OR 1.956 (95% CI 1.522–2.515); p<0.001] after adjusting for age, sex, BMI, smoking, and drinking." (PMID 29211729, 2017). "We aimed to evaluate the associations of single nucleotide polymorphisms (SNPs) in APOA5, including -1131T>C and c.553G>T, with hypertriglyceridemia, apoA5 concentrations, atherogenic LDL cholesterol levels, and arterial stiffness in hypertriglyceridemic patients." (PMID 29211729, 2017). "APOA5 rs3135506, which predisposes to hypertriglyceridemia in homozygous form, was 1.8–fold more frequent in the affected individuals of the FCH families than in the general population (minor allele frequency [MAF] in affected FCH individuals = 0.11, MAF in population = 0.062)." (PMID 27227539, 2016). "Our findings indicate that genetic variants play an important role in severe hypertriglyceridemia during pregnancy, and, p.G185C mutation in APOA5 gene might be a common variant in individuals of Chinese descent." (PMID 26079787, 2015). "Although the association between APOA5 genetic variants and hypertriglyceridemia has been extensively studied and also replicated in our study, there have been few studies, particularly in children and adolescents, on the association between APOA5 genetic variants and non-HDL-C levels." (PMID 24903888, 2014). "Recent findings indicate that APOA5 could also influence cholesterol homeostasis and probably could play a role in hypertriglyceridemia associated with diabetes and inflammation." (PMID 24684850, 2014). "Genetic polymorphisms of APOA5 are associated with hypertriglyceridemia." (PMID 23509746, 2013). "Given that the overexpression of hNR1D1 had no beneficial effect on HTG in ApoA5-/- hamsters, which still may predispose animals to the metabolic disease, making us consider to restore ApoA5 to rescue hypertriglyceridemia and fatty liver due to ApoA5 deficiency." (PMID 38505614, 2024).